TOMM5 (translocase of outer mitochondrial membrane 5)
Description:
Component of the translocase of the outer membrane of mitochondria (TOM) complex essential for the recognition and translocation of cytosolically synthesized mitochondrial preproteins. The TOM complex associates with the ion channel VDAC2 and PINK1 kinase at depolarized mitochondria, this interaction stabilizes PINK1 at the outer mitochondrial membrane and triggers downstream mitophagy by the recruitment of the E3 ubiquitin ligase PRKN.
Synonyms: C9orf105; TOM5; bA613M10.3
Tractability: Small molecule: a structure with a bound ligand is known. Antibody: UniProt predicts a signal peptide or a membrane-spanning region. PROTAC: UniProt records ubiquitination sites on it; ubiquitination databases record sites on it; its protein half-life has been measured.
Gene: Protein-coding gene on chromosome 9 (37,582,646 to 37,592,609, reverse strand). Ensembl gene ENSG00000175768.
Subcellular location: Mitochondrion outer membrane
Subcellular location (Human Protein Atlas): Mitochondria
Pathways (Reactome):
Autophagy: PINK1-PRKN Mediated Mitophagy
Protein localization: Mitochondrial protein import
Gene Ontology:
Biological process: protein insertion into mitochondrial outer membrane; protein localization to mitochondrion
Cellular component: mitochondrial outer membrane translocase complex; mitochondrion; mitochondrial outer membrane; TOM complex
Genetic constraint (gnomAD): Loss-of-function variants: 1 observed, 3.59 expected, observed/expected ratio (o/e) 0.28, 90% interval 0.098 to 1.28. That is too few expected variants to judge how well the gene tolerates losing a copy. Missense variants: 49 observed, 58.93 expected, observed/expected ratio (o/e) 0.83, 90% interval 0.66 to 1.05. Synonymous variants: 24 observed, 24.64 expected, observed/expected ratio (o/e) 0.97, 90% interval 0.7 to 1.37.
Homologues: Orthologues: rabbit TOMM5 (100% identical), guinea pig TOMM5 (98% identical), zebrafish tomm5 (82% identical), tropical clawed frog tomm5 (69% identical).
Diseases named in the same sentence as TOMM5 in open-access papers:
TOMM5 is named in the same sentence as 10 diseases in open-access papers, as found by Europe PMC text mining. Sharing a sentence is not in itself a finding about the gene and the disease. The quoted sentences say what the papers report.
diabetes (2 papers, 2022 to 2023). "Functional analysis and lncRNA-mRNA network analysis showed that it contained many genes that have been reported to be related to diabetes and vascular diseases, such as TOMM5, MYLK, PDLIM1, and CAMK2G." (PMID 35508613, 2022). "TOMM5 and DNAJB9 have been reported to be involved in the development of cancer, type 2 diabetes mellitus, and obesity; however, few studies of TOMM5 and DNAJB9 on IVDD have been reported." (PMID 38041088, 2023). "The related genes such as TOMM5, and MYLK have been reported to have implications in diabetes, and PDLIM1 and CAMK2G were found to be related to atherosclerosis." (PMID 35508613, 2022).
Obesity (2 papers, 2013 to 2023). Accumulation of substantial excess body fat. "TMBIM4 is located within ±1 Mb of the SNP rs1531343 conferring susceptibility to T2DM, while NCKAP5L, TOMM5, and BAP1 are mapped within ±1 Mb of SNPs conferring susceptibility to obesity." (PMID 24455749, 2013). "Using the same method, seven highly ranked genes (BAP1, GRB14, HSP90AB1, ITGA5, NCKAP5L, SP1, and TOMM5) within ±1 Mb of obesity SNPs were identified." (PMID 24455749, 2013). "The rest of the candidates, C2orf15, DENND1B, MRPL30, POC1B, RP4-655J12.3, TMBIM4, BMP2 K, CSRNP2, NCKAP5L, TOMM5, and BAP1, may be novel genes related to T2DM or obesity." (PMID 24455749, 2013).
lung diseases (1 paper, 2023). "According to their findings in this mouse model, defective TOMM5 alleles could contribute to an increased susceptibility to certain lung diseases in humans and animals." (PMID 37035734, 2023).
TOMM5 also shares sentences with these, for which no sentence is quoted: glioma (2 papers); tumor (2); atherosclerosis (1); cancer (1); degenerative joint diseases (1); genetic disorders (1); type 2 diabetes mellitus (1).